CD4 (CD4 molecule)
Diseases named in the same sentence as CD4 in open-access papers (continued):
Sharing a sentence is not in itself a finding about the gene and the disease.
AIDS (continued). "The idea that the rate of CD4 cell decline is informative seems to have its origins in studies showing that AIDS is often preceded by a sudden fall in CD4 cell count." (PMID 20186270, 2010). "Characteristics of 3,078 AIDS-free patients from the CASCADE collaboration with a CD4 cell count in 1993 and at least one prior CD4 cell count." (PMID 20186270, 2010). "In the “current practice” scenario, mean CD4 count at diagnosis was 308/μl among prevalent cases and 370/μl overall; 25% of patients were diagnosed after presenting to care with an AIDS-defining opportunistic disease (Table A2)." (PMID 20976112, 2010). "Among the AIDS-free untreated adolescents, the CD4+ T-cell trajectory from one visit to the next in the absence of any ART therapy (i.e. every 3 months on average) was associated with multiple SNP genotypes." (PMID 20976276, 2010). "Outcomes analyzed were virologic suppression (VS) and failure (VF), CD4 count changes, AIDS and death." (PMID 20507622, 2010). "IBD serological markers (ASCA, pANCA, anti-OmpC, and anti-CBir1) were measured by ELISA in plasma from AIDS patients (n = 26) with low CD4 counts (<300 cells/μl) and high plasma LPS levels, and results correlated with clinical data." (PMID 21125014, 2010). "The intriguing progression to AIDS in the presence of normal or high levels of CD4+T cells counts suggest these to be functionally altered." (PMID 20028500, 2009). "Such a population would therefore be missing the benefits of timely introduction of HAART, such as the reported threefold reduction of AIDS incidence when HAART is administered to patients with CD4 cell counts below 200 cells/mm3." (PMID 19405971, 2009). "Among these late presenters, the contribution of person-years was much larger among heterosexuals, MSM, and PWHA born outside Italy, whereas HAART use was rarer and median CD4+ cell count at AIDS diagnosis was lower than in other PWHA." (PMID 19223894, 2009). "Unfortunately, a substantial proportion of IDUs in the United States received a concurrent diagnosis of HIV and AIDS, and 38.2% of these persons had very low CD4+T-cell counts at HIV diagnosis (<50 cells/μL)." (PMID 19214229, 2009). "As infection progresses, CD4 declines and should, in principle, provide a measure of the remaining time to AIDS and death." (PMID 19536329, 2009). "In contrast, for a patient with CD4 count at the lower 75th centile, relative risks increased from 1.0 at seroconversion to maxima of 6.3 (4.4–8.9) for AIDS and 5.5 (2.7–10.1) for death by year 6, when the population median had fallen to 300 cells/μL." (PMID 19536329, 2009). "In contrast to this, CMV-specific CD4+ T cells persist in large numbers, even in individuals with AIDS." (PMID 19876388, 2009). "Many patients start treatment late, with a history of AIDS defining illnesses and low CD4 cell counts." (PMID 19399157, 2009). "Since the level of CD4+ T cells in the blood of HIV-infected patients is predictive of the onset of AIDS, we wished to explore this second pattern in greater detail." (PMID 19360097, 2009). "Two hundred and twenty-eight consented People Living with HIV/AIDS (PLWHAs) who were placed in three groups according to their CD4 counts were used in the study." (PMID 19922646, 2009). "One of these animals developed AIDS, as shown by peripheral blood CD4+ T-cell depletion starting at 20 weeks post inoculation." (PMID 19602283, 2009). "More importantly for AIDS pathogenesis, the level of autoreactive antibodies significantly correlated with the extent of naïve CD4+ T cell depletion." (PMID 19360097, 2009). "Most of our study patients (73%) had CD4 count <200 cells/μl, which is considered as AIDS defining advanced stage." (PMID 19479058, 2009). "We used standardized Kaplan-Meier survival methods to determine differences in time of progression from HIV to AIDS and death, by race/ethnicity, sex, age group, CD4+ T-cell count, metropolitan residence, and diagnosis year." (PMID 19214229, 2009).
AIDS (continued). "As of 2008, the common protocol in USA and Western Europe is to initiate treatment when CD4 falls below 350/μL or in case of a history of an AIDS-defining illness." (PMID 19536329, 2009). "A 29-year-old African American woman with AIDS (CD4 count of 8 cells/uL) presented with three weeks history of weakness, non-bloody, non-mucoid diarrhea and esophageal candidiasis." (PMID 20181177, 2009). "HIV infects and depletes CD4+ T lymphocytes, putting patients at risk for opportunistic infection and malignancy, the major causes of death due to HIV and AIDS." (PMID 19680452, 2009). "Anti-CD4+ T cell antibodies were reported soon after identification of AIDS, and a role in CD4+ T cell decline was suggested." (PMID 19360097, 2009). "It should be stressed that the information on hospital characteristics was gathered for other purposes than this study and some vital features of HIV/AIDS patients are missing, such as CD4 counts and viral load." (PMID 19627574, 2009). "Subjects in the early ART arm spent less time with CD4 counts <50 or <100 and therefore the “window of vulnerability” to additional AIDS-related complications was shortened by early use of ART." (PMID 19440326, 2009). "This child, aged 45 months at enrollment, was severely immunocompromised [CD4+ cells ranged between 298 (16%) and 548 (18%)] and had clinical category B AIDS." (PMID 19698184, 2009). "IDUs with a diagnosis of HIV at older ages or with more severe disease (lower CD4+ T-cell count at AIDS diagnosis) had shorter survival." (PMID 19214229, 2009). "Guidelines for the use of antiretroviral medications in adults and adolescents infected with HIV type 1 recommend initiating treatment in patients with a history of an AIDS-defining illness or with a CD4+ T-cell count of <350 cells/μL." (PMID 19214229, 2009). "Left untreated, human immunodeficiency virus type-1 (HIV) generally targets and severely depletes a patient's CD4+ T cells over a period of up to 15 years, with a median AIDS onset time of 9.8 years." (PMID 19680436, 2009). "The World Health Organization (WHO) currently recommends that all HIV-infected TB patients receive co-trimoxazole and that patients with clinical evidence of AIDS or CD4+ T-lymphocyte counts (CD4) <350 cells/μL initiate ART during TB treatment." (PMID 19364398, 2009). "The major factor involved in the development of AIDS is the depletion of uninfected, bystander CD4 T cells, while the population of macrophages remains unaffected." (PMID 19492063, 2009). "Since it is difficult to determine the moment of infection, low CD4+-cell count at diagnosis or rapid progression to AIDS have been used to define late presentation." (PMID 18416849, 2008). "In this instance, among subjects in whom a high CD4 count would have predicted a lower likelihood of developing AIDS, a high and moderate GRG identified subsets of subjects with increased likelihoods of developing AIDS." (PMID 18776933, 2008). "We therefore conducted an analysis of longitudinal data from the Cape Town AIDS Cohort (CTAC) in South Africa in which CD4 cell counts and VL measurements are routinely measured every three months." (PMID 18601727, 2008). "Expression of consensus nef genes from the two pre-AIDS clones, 8G9 and 32D2, induced the highest level of CD4 downmodulation, similar to that of the NL4-3 nef gene." (PMID 18510766, 2008). "Approximately 60% had a previous diagnosis of AIDS based either on an opportunistic infection or a CD4 cell count below 200 cells/μl." (PMID 18796158, 2008). "Nonetheless, CD4 depletion and AIDS occur in patients from which only CCR5-using viruses can be isolated." (PMID 18205925, 2008). "Relatively high levels of HIV DNA and RNA were detected in CD4+ T-cells from 8 of 8 and 4 of 6 AIDS patients, respectively, whereas levels were below the limit of detection in Mo from 6 of 8 and 5 of 6 patients, respectively." (PMID 18575590, 2008).
AIDS (continued). "We show that infection of macaques with either SHIV-1157i or with passaged virus leads to depletion of both memory and total CD4+ T cells, resulting in AIDS and multiple opportunistic infections in some monkeys." (PMID 18928523, 2008). "A LR of >1 or <1 indicates a greater or lower likelihood of developing AIDS, respectively, and we found that the three CD4 and viral load strata as well as a low, moderate and high GRG status were each associated with predictable LRs." (PMID 18776933, 2008). "Unfortunately, some patients infected with the nef-deleted virus eventually lose their CD4+ T cells to levels indicating progression to AIDS." (PMID 18808677, 2008). "From this study it appears that the CD4 counts and prevalence of the protozoal infection in a particular geographic area should be considered before instituting empirical therapy to the AIDS patients attending the ART centre." (PMID 18713475, 2008). "Of all the factors concerning the seroprevalence rate being studied (age, sex, intravenous drugs use, alcohol consumption, CD4 levels, AIDS, HCV, HBV, residential area), only age was statistically significant." (PMID 18452613, 2008). "<100 cells/μl represents a very low CD4+ count, <200 is AIDS defining, 350 is the lower end of the normal range for men." (PMID 18560573, 2008). "Patient clinical status, CD4 count at time of virus isolation, time to/from AIDS diagnosis and coreceptor use of primary isolates studied." (PMID 18371209, 2008). "She told, “Davai Khani hai, CD4 jaida hai ate AIDS hon vich time lagda hai” (The doctor told me that my CD4 count was high; it takes time for the development of AIDS, so I have to take the medicine)." (PMID 19876484, 2008). "The first patient (case 9) was a 31-year-old intravenous drug addict with AIDS (CD4 count 132 cells/mm3) and acute infective endocarditis who developed dry gangrene of her right hand and both feet." (PMID 18513426, 2008). "Ten KS cases arose in PWHA whose CD4 cell count was very low despite concurrent HAART use whereas 5 MSM developed KS despite being on HAART and having CD4 cell counts at which AIDS-related KS is seldom seen." (PMID 18665172, 2008). "Even though 32.3% of patients reported a CD4 cell count less than 200, the group as a whole seem to be "extremely ill"; 66.4% self-reported to have been diagnosed with AIDS." (PMID 19102765, 2008). "Most important, these conclusions suggest that the design immunogens which selectively elicit CD4+ T cell responses capable of “self-protection” against HIV-1 is a potential new strategy in the quest for an AIDS vaccine." (PMID 18941536, 2008). "The United States Guidelines recommend to start ART when CD4 is < 25% while the Pediatric European Network for Treatment of AIDS recommend starting ART at CD4 < 20% in children ages 1 to 3 years and CD4 < 15% in older children." (PMID 18957095, 2008). "Regarding various disease characteristics (self-reported AIDS diagnosis, hospitalization, CD4 cell counts, ART and traditional medicine); only being on ART was in this study associated with HIV symptom intensity." (PMID 19102765, 2008). "sTNFR p55 and interferon-γ showed appreciable and highly significant differences between groups of patients with AIDS related diarrhoea and different CD4 counts (groups 3 and 4)." (PMID 19014537, 2008). "Annual incidence of AIDS (%) and numbers needed-to-treat according to baseline CD4+ T cell count, the steady-state viral load and CCL3L1-CCR5 GRG, based on Poisson regression model." (PMID 18776933, 2008). "HIV DNA and RNA were low in circulating Mo compared to CD4+ T-cells, suggesting that Mo represent a minor site for HIV replication compared to CD4+ T-cells in AIDS patients." (PMID 18575590, 2008). "In the terminal stages of AIDS, where CD4+ lymphocyte counts falls below 100, not only M. tuberculosis but several NTM also cause infection and can be isolated from blood, tissue, sputum and fecal samples." (PMID 18620572, 2008).
AIDS (continued). "PD-1 is also expressed on activated CD4+ T cells and its blockade partly restored CD4 proliferative responses in AIDS patients." (PMID 18636106, 2008). "In summary, by using a common event (AIDS), we were able to directly compare evolution of CD4 T-cell count and HIV RNA level after HIV-1 seroconversion." (PMID 17888148, 2007). "We modeled the simultaneous evolution of CD4 and viral load using follow-up data from seroconversion until AIDS diagnosis." (PMID 17888148, 2007). "Mechanisms by which HIV-1 mediates reductions in CD4+ cell levels in infected persons are being intensely investigated, and have broad implications for AIDS drug and vaccine development." (PMID 18028545, 2007). "The incidence in persons with CD4 counts <200/mm3 (2.5/100 person-years) was clearly lower than in AIDS patients in the United States before the introduction of routine trimethoprim-sulfamethoxazole prophylaxis and highly active ART (10/100 person-years)." (PMID 17479904, 2007). "Ten to 15% are rapid progressors who have a fast CD4+ T-cell decline and occurrence of AIDS-related events within a few years after infection." (PMID 17502001, 2007). "There was a higher mean HIV viral load in both the serum and BAL of subjects with CD4 counts less than 200 cells/μl (clinical AIDS) than in HIV infected subjects with higher CD4 counts." (PMID 17567900, 2007). "Most of the subjects with HIV disease attend HIV testing centers in India only after advanced clinical HIV disease (AIDS) sets in and when their CD4+ T-cell counts are low." (PMID 18053126, 2007). "We also compared the levels of MBL among normal subjects, HIV positive subjects with CD4 count > 200 and AIDS patients (CD4 count <200 cells/μl)." (PMID 17567900, 2007). "Among HIV infected patients, patients with AIDS had a higher SP-D than patients with higher CD4 counts." (PMID 17567900, 2007). "In terms of the CD4 data, the estimated correlation between pooled endpoints from a BRMA enables one to predict the time of onset of AIDS or death from a future patient's CD4 level." (PMID 17222330, 2007). "According to the guideline for management of HIV-infected patients in Thailand, ART is recommended for all patients with history of AIDS-defining illness or asymptomatic patients with CD4 cells count less than 200 cell/mm3." (PMID 17352834, 2007). "In 1993, the AIDS case definition was expanded to include CD4 count<200 cells/μl as an AIDS-defining criterion." (PMID 17579722, 2007). "For CD4 T-cell count, on the other hand, the decline (on cube root scale) changed from -0.43 to -1.27 per year at 1.5 years before AIDS diagnosis, and this change in slope was significant (95% CI 0.66 to 1.02)." (PMID 17888148, 2007). "HIVD was the subjects first and only AIDS defining illness, and coincided with the CD4+ T-cell count falling below 200 cells/μl and plasma viral load steadily increasing to approximately 20,000 RNA copies/ml." (PMID 19088897, 2007). "The emergence of CXCR4 strains during the course of an infection is correlated with increased CD4+ T cell depletion and accelerated progression towards AIDS." (PMID 17945027, 2007). "One individual SNP (SNP6 A/G) appears responsible for the rapid CD4 T cell depletion and progression to AIDS." (PMID 17651505, 2007). "The evolution of HIV infection from the fusion of the first virion with a CD4+ T-cell to AIDS and death is influenced by a multitude of interacting factors." (PMID 17502001, 2007). "A CD4+ T cell count below 200 cells/mm3 and infection with at least one opportunistic infection, such as Pneumocystis Carinii defines clinical AIDS." (PMID 17945027, 2007). "The majority of infected individuals (70–80%) experience intermediate disease progression in which they have HIV-RNA rise, CD4+ T-cell decline and development of AIDS-related illnesses within 6–10 years of acquiring HIV." (PMID 17502001, 2007).
AIDS (continued). "Cox survival analysis and mixed effects models were used to assess time to AIDS outcomes and CD4+ T cell trajectories, respectively." (PMID 17257057, 2007). "CD4 count<200 cells/μl usually precedes the diagnosis of an AIDS-OI, and most cases are now reported based on this immunologic criterion." (PMID 17579722, 2007). "We also compared the levels of SP-D among normal subjects, HIV positive subjects with CD4 count >200 cells/μl and patients with AIDS (CD4 count <200 cells/μl)." (PMID 17567900, 2007). "Prior AIDS diagnoses (one participant) and low CD4 cell counts (eight participants) accounted for all ineligible screens." (PMID 16871325, 2006). "A recent French study of HIV therapy-naïve patients between 1996–2002 used a survival analysis to determine the relative value of the CD4 percentage and count in describing the probability of an AIDS-related event or death." (PMID 16916461, 2006). "Patients with lymphoreticular malignancies or AIDS are at risk of disseminated MAC infection, usually when the CD4+ count is <50 μL." (PMID 17054802, 2006). "The hazard ratio of progression to AIDS or death before April 1997 was 50.8 (p<0.01) in CD4 cell counts of less than 200 cells/μL and 7.7 (p=0.05) in those of 200-349 cells/μL compared with those of 500 cells/μL or more." (PMID 16710078, 2006). "The extent of immunosuppression and the probability of developing an AIDS-related complication in HIV-infected people is usually measured by the absolute number of CD4 positive T-cells." (PMID 16916461, 2006). "Although women with HIV/AIDS had lower fertility and BMI in the pre-HAART era, the breast cancer deficit with AIDS was minimally altered by adjustment for these factors, and it was unrelated to CD4 count or AIDS-relative time." (PMID 16868538, 2006). "The CD4 percentage was an unsurpassed predictor of the occurrence of AIDS-related events when all subsets of patients are considered." (PMID 16916461, 2006). "Variables included in the logistic regression model were vaccine dose, CD4 count, viral load, HAART treatment, AIDS-defining illness, gender and risk factor for HIV infection." (PMID 16600028, 2006). "The Centers for Disease Control definition of AIDS allows the measurement of the CD4 percentage as an option for the diagnosis of AIDS and as an option for instituting pneumocystis prophylaxis (but not for toxoplasma or MAI prophylaxis)." (PMID 16916461, 2006). "Hazard ratios of CD4 cell count in the first quarter of 1994 for progression to AIDS or death before 1997." (PMID 16710078, 2006). "Majority of the study population were in advanced stage of HIV disease (AIDS), confirmed by clinical staging and CD4 level." (PMID 16509972, 2006). "The hazard ratio of a CD4 cell count of less than 200 cells/μL for progression to AIDS or death after 1997 was 4.7." (PMID 16710078, 2006). "If only patients who meet the CDC definition of AIDS are analyzed (CD4 count <200), the CD4 absolute count is a better predictor of the true to onset of an event." (PMID 16916461, 2006). "More than 50% of those children had diagnosis of AIDS previous to baseline; 29/42 of children had CD4+ T-cells <25% whereas 14/42 had VL >50.000 copies/ml." (PMID 16834769, 2006). "With the exception of patients who have a CD4 absolute count below 200 and thus have AIDS by the Centers for Disease Control's definition, the CD4 percentage is superior or equivalent to the CD4 absolute count in various subsets of HIV infected patients." (PMID 16916461, 2006). "The AIDS-free proportion was lower where the CD4 cell count was less than 200 cells/μL, with plasma HIV RNA levels of 50,000 copies/mL or more and also lower in 2 NRTIs + 1 PI than in the others." (PMID 16710078, 2006). "We subdivided the patients according to their CD4+ T cell count, i.e. twelve samples with >200 cells/μl and eight samples with <200 cells/μL (AIDS)." (PMID 16817969, 2006).